CRISP3 (cysteine rich secretory protein 3)
Diseases named in the same sentence as CRISP3 in open-access papers (continued):
Sharing a sentence is not in itself a finding about the gene and the disease.
tumor (continued). "Through RNA-seq in 3 pairs of ESCC tumor and paracancerous tissues and qRT-PCR experiments on 38 pairs of tumor and paracancerous tissues, we found that the expression level of CRISP3 in tumor tissues was significantly higher, and it was closely related to tumor development and metastasis." (PMID 36263172, 2022). "Our study showed that overexpression of hsa_circ_0003823 significantly enhanced the invasion and migration ability of tumor cells, and increased the expression levels of CRISP3 and metastasis-related proteins, while knockdown of hsa_circ_0003823 had the opposite effects." (PMID 36263172, 2022). "The LINC01342/CRISP3 silencing or miR-508-5p elevation inhibited proliferation, migration, and invasion of LC cells and promoted LC cell apoptosis, and also suppressed the in vivo tumor growth." (PMID 34504061, 2021). "Interestingly, while CRISP3 was detected in both PCa samples and in the tumor-derived VCaP cells, the benign prostate cell line PNT2 showed no detectable expression (data not shown)." (PMID 21814574, 2011). "As IL-17 is a signature cytokine of these cell types, CRISP3 may both promote tumor cell proliferation via IL-17/AKT signaling and facilitate the recruitment or expansion of IL-17–producing immune cells, thereby reinforcing an immunosuppressive tumor microenvironment." (PMID 41200166, 2025). "Targeting CRISP3, d-glucopyranose may impact tumour prognosis." (PMID 37070095, 2023). "Taken together, these evidences confirm that these HEMTIRGs (CRISP3, PAX7, FGG, and DCD) are closely related to hypoxia, EMT, and tumor immunity, which in turn contribute to the regulation of BC pathogenesis and prognosis." (PMID 41200166, 2025). "Several genes particularly CXCL14, COX6C, CRISP3, and MPG with high expression levels in these tumor regions were identified, while healthy cells exhibited few significant genes, with only MALAT1 observed." (PMID 39764614, 2024). "Therefore, the increased CRISP3 could promote tumor generation in obese individuals." (PMID 39609876, 2024). "P08-029pre, which came from a small tumor volume of 0.6 cc, showed marginal increase (2- to 3-fold above background) for these genes except for AMACR: AGR2 = 0.16, AMACR = 0.32, CRISP3 = 0.78, ERG = 0.28, HPN = 0.12, PCA3 = 0.19." (PMID 23029164, 2012). "According to the studies, we found that the upregulation of CRISP3, S100A13, and S100A16 in domain 3 suggests that this region possesses tumor invasiveness, metastatic potential, and an active inflammatory environment, thereby promoting tumor progression." (PMID 41223185, 2025). "Therefore, our study found that during PCa pathogenesis, the disorganized expression of CRISP3, OGN, SPOCK3, COL4A6, CCBE1, and FLRT3 leads to ECM dysfunction and promotes angiogenesis and tumor development." (PMID 37251946, 2023). "In addition, we also examined the expression level of CRISP3 in 38 pairs of ESCC tumor and paracancerous tissues, and the results showed that the expression level of CRISP3 was significantly higher in tumor tissues." (PMID 36263172, 2022). "GRN, CD5L, ENO1, CHL1, CRISP3, VASN, and TNIK promote the invasive ability of tumor cells." (PMID 32953262, 2020). "Moderate/high CRISP3 protein expression was present in 217/316 (69%) in ERG positive vs. 287/496 (58%) in ERG negative tumor cores (p = 0.002)." (PMID 24606912, 2014). "We further show that CRISP3 is a direct target of overexpressed ERG, suggesting that CRISP3 may be a mediator of tumor progression driven by the TMPRSS2-ERG rearrangement." (PMID 21814574, 2011). "We observe decreased CRISP3 levels in bone marrow specimens from MM patients compared to the NCBD group (p < 0.05), as well as downregulated expression in the MM group with poor prognosis (p < 0.05), which further characterizes it as a potential tumor suppressor." (PMID 39769169, 2024). "Therefore, CRISP3 related to DES has been correlated with a poor prognosis in PCa, and it may induce tumor proliferation by promoting EMT." (PMID 37070095, 2023).
tumor (continued). "Interestingly, there were four tumor suppressors significantly stimulated after YB, namely, deleted in malignant brain tumor 1 (DMBT1), mucin-7 (MUC7), cysteine-rich secretory protein 3 (CRISP3), and prolactin-inducible protein (PIP)." (PMID 25873979, 2015). "In the 24 prostatectomy specimens analyzed by expression arrays, CRISP3 was classified as over-expressed in 62.5% of tumor samples (8 ERG positive and 7 ERG negative) as compared to the non-malignant prostatic tissue, with the remaining showing normal/decreased protein expression." (PMID 21814574, 2011).
cancer (18 papers, 2009 to 2024). A tumor composed of atypical neoplastic, often pleomorphic cells that invade other tissues. "Recent studies revealed that CRISP3 was inextricably linked to cancer." (PMID 36263172, 2022). "Dysregulated CRISP3 was related to the undesirable prognosis of several cancers, and CRISP3 was determined as a therapeutic target for those patients." (PMID 39624089, 2024). "The expression of CRISP3 is intimately connected with the characteristics of cancer stem cells, playing a key role in the self-renewal and multilineage differentiation potential of tumors." (PMID 39418177, 2024). "The most significantly upregulated DEGs such as SNCG, CPNE8, GRIA3, SOX5 and CRISP3 can be involved in metastasis and invasivity of cancer cells as well." (PMID 37239828, 2023). "Several genes that encode these proteins were upregulated in the CD26+ cancer cells: AGR2, BCMP11, CEACAM5/CD66e, CRISP3, KCNG3, KCNH8, LOX and NEO1." (PMID 20021671, 2009). "Despite the fact that CRISP3 expression has been linked to the genesis and progression of prostate and breast malignancies, CRISP3 exhibited non-significant expression in pan-cancer tissues, and ADH1B has been verified in cancer; therefore, CLU was selected." (PMID 36685863, 2022). "CRISP-3 was found to be associated with high Gleason grade with elevated intensity, and it was also overexpressed in high-grade prostatic intraepithelial neoplasia (HG-PIN), which indicates that CRISP-3 could be a marker for early cancer development." (PMID 24371818, 2013). "CRISP3 is an abundant protein of the human seminal plasma and interacts with alpha-1-B glycoprotein (A1BG), a human plasma glycoprotein that is upregulated in different types of cancers." (PMID 39433128, 2024). "Strikingly, the top-ranked gene – CRISP3 – showed a massive fold increase in ERG-positive carcinomas as compared to both non-malignant tissue and ERG-negative carcinomas, which led us to validate and study this candidate target further." (PMID 21814574, 2011). "Furthermore, immunohistochemistry results showed CRISP3 protein overexpression in 63% of the carcinomas and chromatin immunoprecipitation with an anti-ERG antibody showed that CRISP3 is a direct target of the transcription factor ERG." (PMID 21814574, 2011). "We observed a massive fold-increase of CRISP3 in fusion-positive carcinomas as compared to non-malignant tissue or fusion-negative carcinomas and found that ERG genomic rearrangement and ERG and CRISP3 mRNA overexpression are associated with pT3 locally advanced tumors." (PMID 21814574, 2011). "For most surrogate peptides measured, the cancer urine showed higher median L/H values than non-cancer urine; while for several others (CRISP3, CXL14, IL24 and SFRP4), a lower or equal median L/H value in cancer vs. non-cancer was found." (PMID 29254211, 2017).
infection (5 papers, 2014 to 2024). The state of being infected such as from the introduction of a foreign agent such as serum, vaccine, antigenic substance or organism. "Furthermore, CRISP3 was found to be homologous to pathogen-resistant proteins induced by infection in plants, which further supported the concept that CRISP3 may be an immunoregulatory factor." (PMID 39624089, 2024). "While most genes found in this dataset in lung or spleens are also upregulated in VN1203 infection, CRISP3 is upregulated by BC500 in the lung on all 3 dpi, but not at all in VN1203 infection." (PMID 34804075, 2021).
CRISP3 also shares sentences with these, for which no sentence is quoted: lung carcinoma (3 papers); COVID-19 (2); idiopathic pulmonary fibrosis (2); varicocele (2); adenocarcinoma (1); Anxiety (1); asthma (1); chronic pancreatitis (1); colon cancer (1); dengue (1); esophageal squamous cell carcinoma (1); invasive carcinoma (1); leukemia (1); myopia (1); Obesity (1); trauma (1); type 1 diabetic (1); vitamin D insufficiency (1).